ABCG2 (ATP binding cassette subfamily G member 2 (JR blood group))
Diseases named in the same sentence as ABCG2 in open-access papers (continued):
Sharing a sentence is not in itself a finding about the gene and the disease.
cancer (continued). "To this end, we examined the protein expression of ABCB1 in KB-V-1 cancer cells and ABCG2 in S1-M1-80 cancer cells by immunoblotting after treating cells with sitravatinib at various concentrations (100–500 nM) for 72 h as described in Materials and Methods." (PMID 31941029, 2020). "In this study, we investigated the efficacy of methyl-cantharidimide (MCA), a cantharidin (CTD) analog, as an anticancer drug, in cancer cells overexpressing either ABCB1 or ABCG2 transporters and in cisplatin-resistant cancer cells." (PMID 32676451, 2020). "If our results can be translated to humans, they suggest a novel strategy of combining poziotinib with certain anticancer drugs to treat CRC patients with MDR cancer due to the overexpression of ABCG2 and/or ABCB1 transporters." (PMID 33158067, 2020). "ABCG2 contributed to cancer progression due to its active efflux of chemotherapeutic agents out of neoplastic cells." (PMID 33628166, 2020). "ABCG2 promotes autophagy in cancer cell lines exposed to stressors such as nutrient deprivation, although the ability of the 141K allele to impair autophagy is not yet established." (PMID 32164793, 2020). "ABCG2 is a member of the ATP-binding cassette (ABC) transporter family that is closely related to multidrug resistance (MDR) in cancer treatment." (PMID 32477940, 2020). "The findings based on our in vitro experiments led us to determine the effect of EC16-1/saporin in the parental and the ABCB1- and ABCG2-overexpressing cancer cells using mouse xenograft tumor models." (PMID 32098067, 2020). "Treatment of these cell lines with 5-aza-dC resulted in ABCG2 promoter demethylation, upregulation of ABCG2 and decreased anti-cancer drug sensitivity, indicating that in these cell lines, ABCG2 promoter methylation played a role in ABCG2 gene regulation." (PMID 33066132, 2020). "ABCG2 (also referred to as breast cancer resistance protein (BCRP)) is responsible for therapeutic resistance by mediating the efflux of several anti-cancer agents, including etoposide." (PMID 33066509, 2020). "In the present work, the potential chemosensitization effect of erdafitinib on multidrug-resistant cancer cells was assessed in human cell lines overexpressing ABCB1 or ABCG2." (PMID 32466597, 2020). "It would provide a rational in clinical applications using combination of AZ-628 for overcoming ABCG2-mediated MDR cancers." (PMID 33364237, 2020). "MTT assay in vitro and xenograftes in vivo were used to investigate reversal effect of FW-04-806 on MDR in ABCB1 or ABCG2 overexpressing cancer cells." (PMID 31472682, 2019). "We reveal that in vitro TMP195 treatment significantly enhances drug-induced apoptosis and sensitizes multidrug-resistant cancer cells overexpressing ABCB1 or ABCG2 to anticancer drugs." (PMID 31905792, 2019). "ABCG2 is also expressed by cancer cells and mediates resistance to anticancer agents by promoting the efflux of these drugs." (PMID 31340525, 2019). "For ABCG2, the result showed that the positive expression of ABCG2 was found in 25 out of 39 cancer tissues (P=0.003)." (PMID 31341476, 2019). "ABCG2 is considered a marker of CSCs in some cancers, and responsible for the side-population effect." (PMID 34322663, 2019). "The ABC transporters (ABCG2), act as a resistance marker in both cancer stem cells and cancer cells and help in the determination of prognosis of malignancies and also drug bioavailability." (PMID 31801262, 2019). "The expression levels of stemness genes, including Oct-3/4, Nanog, ALDH1, and ABCG2, were significantly downregulated in YB-1 knockout cancer stem cells compared with those in YB-1 wild-type cancer stem cells." (PMID 31375149, 2019). "Hyperthermia treatment downregulated ABCG2 expression in RGK45 as a result of an increased in ROS levels in cancer stem cells." (PMID 30733583, 2019). "Overexpression of ABCG2 in cancer cells confers significant resistance to PF-4989216, which can be reversed by an inhibitor or competitive substrate of ABCG2." (PMID 31277692, 2019).
cancer (continued). "In such situations, since the patients will be treated with febuxostat before and during chemotherapy, there would be drug-drug interactions between febuxostat and ABCG2 substrate anti-cancer agents." (PMID 30890942, 2019). "We also reported that enhancing the intracellular mitROS concentration by hyperthermia resulted in downregulation of ABCG2 in cancer cells." (PMID 31426474, 2019). "In comparison, TMP195 was least effective in reversing ABCG2-mediated resistance to SN-38 in both ABCG2-overexpressing cancer cell lines." (PMID 31905792, 2019). "The expressions of ABCG2 in cancer cell lines and %MFI increase showed statistically significant inverse correlation (r = -0.9388, p = 0.0055)." (PMID 31083682, 2019). "Then we investigated reversal effect of FW-04-806 on MDR in ABCB1 or ABCG2 overexpressing cancer cells." (PMID 31472682, 2019). "Among them, ABCB1, ABCC1 and ABCG2 are highly involved in the acquisition of multidrug resistance (MDR) to cancer chemotherapeutics." (PMID 34322663, 2019). "The human ABCG2 is an important plasma membrane multidrug transporter, involved in uric acid secretion, modulation of absorption of drugs, and in drug resistance of cancer cells." (PMID 31597297, 2019). "ABCG2 is found to be overexpressed in numerous drug-resistant cancers including breast, ovarian, liver, lung, and melanoma, and it correlates with poor prognosis." (PMID 31814840, 2019). "Primary NB tumor cells have elevated expression of ABC transporters including ABCG2, which are responsible for the efflux of therapeutic drugs and subsequent drug resistance and survival of these cancer cells." (PMID 31191243, 2019). "As a MDR machinery in cancer cells and an important drug gatekeeper in tissues like the intestine and the brain, ABCG2 is involved in the efficacy of cancer chemotherapy in patients treated with ABCG2 substrate anti-cancer drugs." (PMID 30890942, 2019). "Our results here revealed that multidrug-resistant cancer cells overexpressing ABCB1 or ABCG2 can be significantly resensitized by TMP195." (PMID 31905792, 2019). "Two decades ago, the ABC transporter G2 (ABCG2) was discovered in drug-resistant cancer cells and human placenta." (PMID 30890942, 2019). "The ABCG2 protein was positively expressed in 64% of cancer tissues compared to the 36% low ABCG2 expression level." (PMID 31341476, 2019). "So far, 49 members of human ABC transporter family have been discovered; among them, P-glycoprotein (P-gp, also referred to ABCB1 or MDR1) and ABCG2 (MXR or BCRP) which are the important members of ABC family attribute to MDR in cancer cells." (PMID 31814840, 2019). "We discovered that TMP195 resensitizes ABCB1-overexpressing cancer cells to paclitaxel, colchicine, and vincristine, as well as resensitizes ABCG2-overexpressing cancer cells to mitoxantrone, SN-38, and topotecan in a concentration-dependent manner." (PMID 31905792, 2019). "The most studied members of the ABC-family of drug efflux pumps in cancer are ABCB1/MDR1/P-gp (P-glycoprotein), ABCC1 and ABCC2 (multi-drug resistance associated proteins 1 and 2; MRP1 and MRP2 respectively), and ABCG2 (breast cancer resistance protein; BCRP)." (PMID 32382711, 2019). "For instance, studies have revealed that FK228 (romidepsin) is a substrate of both ABCB1 and ABCG2, and that continuous exposure to FK228 induces expression of ABCB1 and ABCG2 in cancer cells." (PMID 31905792, 2019). "In the present study, we report an additional function of TMP195 in reversing ABCB1- and ABCG2-mediated multidrug resistance in cancer cells." (PMID 31905792, 2019). "ABCG2 overexpression can render the cancer cells resistant to the ABCG2 substrate chemotherapy agents, such as mitoxantrone, doxorubicin, SN-38, and several TKIs." (PMID 30890942, 2019).
cancer (continued). "Previous studies have shown that D3 receptor antagonists, which have structural homology to tyrosine kinase inhibitors (TKIs) like nilotinib, which are known ABCG2 modulators, have efficacy in cancer cells overexpressing ABCG2 transporters." (PMID 30181510, 2018). "In this study, we found that VS-4718, at non-toxic concentrations, significantly sensitized ABCB1- and ABCG2-overexpressing cancer cells to their substrates in a dose-dependent manner." (PMID 30425643, 2018). "Our findings advocate further clinical investigation of combinations of dacomitinib and conventional chemotherapy in cancer patients with ABCG2-overexpressing MDR tumors." (PMID 29458405, 2018). "Multidrug resistance (MDR) triggered by ATP binding cassette (ABC) transporter such as ABCB1, ABCC1, ABCG2 limited successful cancer chemotherapy." (PMID 29455646, 2018). "Previous research has demonstrated that GLI1 transcriptionally regulates several transmembrane efflux transporters, such as MDR1/ABCB1, MRP1, LRP, and BCRP/ABCG2, which mediate chemotherapy resistance in several cancers." (PMID 29930746, 2018). "We have shown that knock-down of HUGL1 in human mammary epithelial cells leads to upregulation of five transcripts that have been linked to cancer stem cells, side population (SP) cells, or increased invasion in cancers (ABCG2, MMP2, ESR1, THBS1 and KRT19)." (PMID 29361610, 2018). "Cancer side-population (SP) represents a sub-population of stem-like cancer cells that have an important role in drug resistance due to their high expression of the ATP-binding cassette transporter ABCG2 involved in drug export." (PMID 29367724, 2018). "The effects of LS-2-3j on enhancing the sensitivity of ABCB1- and ABCG2-overexpressing cells to conventional anti-cancer drugs were further detected by the intracellular DOX- and MITX-associated mean fluorescence intensity (MFI) using flow cytometry." (PMID 30544754, 2018). "A “multitarget multiribozyme” (MTMR) containing three trans-acting hammerhead ribozymes that, after autocatalytic self-activation, cleave the transcripts of the ABC transporter genes ABCB1, ABCC2, and ABCG2 tested positive in several cancer cell models." (PMID 29401721, 2018). "Among these transporters, the ABC transporter subfamily B member 1 (ABCB1) and the ABC transporter subfamily G member 2 (ABCG2) are known to play an important role in mediating multidrug resistance in cancer cells." (PMID 30544754, 2018). "Owing to the existence of ABCG2, a DNA binding dye, Hoechst 33342 can be pumped out as a substrate, serving as the basis of side-population (SP) assay to identify the stem-like cancer cells in certain types of cancers." (PMID 29367724, 2018). "The over expression of the ATP-binding cassette (ABC) family G2 (ABCG2) transporter is one of the main mechanisms that mediates MDR in cancer." (PMID 30181510, 2018). "Studies have shown that ABCB1 and ABCG2 are overexpressed in many multidrug resistant cancer cells including ovarian, colon, lung, breast, and melanoma cancers." (PMID 30544754, 2018). "The results revealed the expression of CD44, CD133, OCT-4, KLF4 and ABCG2 in the sphere forming cells and verified that cancer stem cells displaying the stemness properties were successfully isolated." (PMID 29559853, 2018). "This study is the first to report that cariprazine, a D3/D2 receptor partial agonist, increases the efficacy of MX (an ABCG2 substrate) in the ABCG2 overexpressing cancer cell lines H460-MX20 and S1M1-80." (PMID 30181510, 2018). "ATP binding cassette (ABC) transporters such as P-glycoprotein (ABCB1), MDR-1 and ABCG2 (BCRP, breast cancer resistance protein) lead to drug efflux and multidrug resistance, which is a major problem in cancer treatment." (PMID 29757250, 2018).
cancer (continued). "For example, Slc2a1 (Glut1) was clustered together with Cldn5 (claudin 5) and Abcg2 (the breast cancer protein) in both cerebral structures, but it was clustered closely only with Abcc1 (multidrug resistance protein 1) in the hippocampus." (PMID 30298005, 2018). "Dacomitinib was first evaluated for MDR reversal in cancer cell models with defined overexpression of ABCG2." (PMID 29458405, 2018). "Tumor initiation cells or cancer stem cell markers ABCG2 and ALDH1 play pivotal roles in invasion, metastasis and resistance to cytotoxic agents." (PMID 31516883, 2018). "ABCG2 expression at both mRNA and protein levels were also evaluated in the resistant ABCG2-overexpressing cancer cells H460/MX20 and S1-MI-80 after treatment with dacomitinib at the MDR reversal concentrations for 48 h." (PMID 29458405, 2018). "Expression of ABCG2 in cancer cells increases resistance to several chemotherapeutic agents such as mitoxantrone, topotecan and methotrexate." (PMID 28281205, 2017). "Disruption of ABCG2 function, through ectopic expression of an ABCG2 dominant negative construct or a specific ABCG2 inhibitor, increased drug sensitivity of cancer cells both in culture and in mice." (PMID 28404967, 2017). "Similar results were obtained with drug selected cancer cells that acquired ABCG2-mediated resistance to mitoxantrone, such as H460/MX20 and S1-M1-80, overexpressing wild-type and 482-G mutant ABCG2, respectively." (PMID 29212189, 2017). "Elimination of TAMs was found to retard tumor growth and to suppress ABCG2 expression in cancer cells, similar to the effects of CBP501." (PMID 28969049, 2017). "The side population (SP) analysis has been used to detect the stem-like cancer cell populations based on their high expression of ABCG2 that exports Hoechst-33342 and certain cytotoxic drugs from the cells." (PMID 28245869, 2017). "Target genes of hedgehog signaling include GLI1, PTCH1 as well as other molecules involved in regulation of cancer cell function, such as ABCG2." (PMID 28404967, 2017). "Breast cancer resistance protein/ABCG2 is an ATP‐binding cassette (ABC) transporter that is one of the proteins responsible for multidrug resistance of cancer cells." (PMID 28922540, 2017). "We have evidence to support that GLI1 is critical for maintenance of putative cancer stem cells through direct regulation of ABCG2." (PMID 28404967, 2017). "Among these members, the three efflux transporters ABCB1 (P-glycoprotein), ABCC1 (the multidrug resistance protein 1 (MRP1)), and ABCG2 are recognized as major contributors to multidrug resistance in human cancer cells." (PMID 28880238, 2017). "Elimination of TAMs by dosing with chlodronate-liposome was performed to evaluate the role of TAMs for ABCG2 expression in cancer cells." (PMID 28969049, 2017). "One earlier report indicates that the interaction between VCAM-1 and CD44 on a cancer cell's surface can induce ABCG2 expression." (PMID 28969049, 2017). "For example, the side population is often enriched in stem cells and cancer stem cells, and ABCG2 is the major gene regulating side population." (PMID 28404967, 2017). "Three ATP-binding cassette (ABC) drug transporters, ABCB1 (p-glycoprotein/MDR1), ABCC1 (MRP1), and ABCG2 (BCRP), have been reported to be critical determinants in the cancer drug resistance." (PMID 28903328, 2017). "Several studies indicate that ABCG2 is potentially involved in cancer drug resistance and increased expression of ABCG2 can increase the risk of drug resistance." (PMID 28948511, 2017). "Of specific interest is the inhibition of ABCG2 as means of sensitizing cancer stem cells to chemotherapy, which is currently under investigation." (PMID 28880238, 2017). "In 2009, An and Ongkeko showed that inhibition of ABCG2 expression can reverse cancer chemoresistance and the reduction of ABCG2 expression can delay cancer chemoresistance." (PMID 28948511, 2017).
cancer (continued). "This expression of ABCG2 was induced by juxtacrine interactions between VCAM-1 on cancer cells and VLA-4 on macrophages." (PMID 28969049, 2017). "ABCG2 pumps out a wide variety of chemical compounds from cells and plays a major role in multi-drug resistance in a number of cancer types." (PMID 27343550, 2017). "ATP-binding cassette sub-family G member 2 (ABCG2) plays a role in side population (SP) cell formation and contributes to chemotherapy resistance in common forms of cancer." (PMID 27911857, 2017). "At the same time, PpIX is excreted from cancer cells into the stromal tissue through ABCG2 (PpIX efflux transporter), resulting in the accumulation of excess PpIX in the stromal tissue in the vicinity of cancer cells." (PMID 28257041, 2017). "The availability of ABCB1 and ABCG2 selective inhibitors should help surmount the selectivity hindrance to the application of JC1 on the isolation of cancer cells over expressing one or the other transporter and somatic stem cells overexpressing ABCG2." (PMID 28380010, 2017). "The PE-cy5.5 conjugated anti-ABCG2 antibody was used to sort ABCG2− (less cancer stem cell-like) and ABCG2+ (more cancer stem cell-like) populations." (PMID 28569775, 2017). "Side population is a functional assay for the transporter ABCG2, and is a well-known readout for stem cells and putative cancer stem cells." (PMID 28404967, 2017). "The indeno[1,2-b]indole scaffold is a versatile and valuable lead structure to develop inhibitors targeting cancer associated proteins like protein kinase CK2, the breast cancer resistance factor and ABC half transporter ABCG2 and the phosphatase CDC25." (PMID 29236079, 2017). "Recently, ABCG2 has been studied as a potential marker of cancer stem cells (CSCs) in diverse human malignances, associated with tumor initiation, maintenance, relapse, metastasis and MDR, which suggests ABCG2 a hopeful target in cancer treatment." (PMID 28029654, 2017). "Several cancer cell stemness markers, such as ABCG2, OCT-4, CD133, ALDH1, CD9, MRP1 and connexin were upregulated in mortalin-overexpressing cells that showed higher ability to form spheroids." (PMID 28165047, 2017). "In contrast, transporters implicated in drug resistance of cancer cells were upregulated in hiPS-Hep cells, including ABCB1 (MDR1) and ABCG2 (BCRP)." (PMID 28137721, 2017). "In the current study, we examined the effect of quizartinib in vitro on wild type and 482-mutant ABCG2-mediated drug resistance in various cancer cells." (PMID 29212189, 2017). "Immunostaining of the original tumours demonstrated that the cancer cells expressed ABCG2 in all five tumours, but to varying extent." (PMID 28877221, 2017). "Although we demonstrated that cytokine production by macrophages induces CSC-like properties, such as anchorage independent proliferation and tumor initiation in cancer cells, the mechanism of induction of the drug resistance marker ABCG2 remained unexplained." (PMID 28969049, 2017). "We have data to show that knocking down GLI1 or inhibiting ABCG2 functions, sensitizes cancer cells to chemotherapy in cultured cells and in mice." (PMID 28404967, 2017). "The clinical relevance of the major ABC-transporters ABCB1, ABCC1, and ABCG2 for failure of chemotherapy and poor survival prognosis of cancer patients has been shown." (PMID 27092478, 2016). "With these validation data and the described scoring guidelines, it is now possible to study the predictive value of ABCG2 in tumor biopsies obtained from cancer patients." (PMID 27257141, 2016). "ABCG2 is expressed not only in cancer tissues but also in numerous normal tissues such as the small intestine and kidney." (PMID 28082903, 2016). "Knowledge of the promoter methylation patterns of ABCB1, ABCC1 and ABCG2 in cancer cell lines will be helpful, e.g. in selecting an appropriate cell line for investigating the mode of action and/or testing the efficacy of potential chemotherapeutic drugs." (PMID 27689338, 2016).